IL1B (interleukin 1 beta)
Diseases named in the same sentence as IL1B in open-access papers (continued):
Sharing a sentence is not in itself a finding about the gene and the disease.
COVID-19 (continued). "The expression of the IL1B gene in COVID-19 patients is closely associated with the TLR4 signaling pathway." (PMID 39622956, 2024). "Cytokines like interleukin (IL) IL-10, IL-17A, and IL-1β play pivotal roles in the inflammatory response associated with severe COVID-19." (PMID 39062105, 2024). "The newly reported genetic variant of ACE2 showed a positive correlation with CD40L, IL-1β, IL-2, IL-15, and IL-17A in COVID-19 patients." (PMID 38855114, 2024). "Cytokines such as TNF-α (tumor necrosis factor), IL-6 (interleukin-6), and IL-1β are implicated not only in the inflammatory response to COVID-19 but also in the development of conditions like major depressive disorder and Alzheimer’s disease." (PMID 39767737, 2024). "This reaction involves the rapid release of high levels of proinflammatory cytokines, such as IL-6, TNF-α, and IL-1β, which are associated with various illnesses, including viral infections (e.g., COVID-19), autoimmune conditions, and sepsis." (PMID 39459194, 2024). "Contrary to our findings, another study on COVID-19 patients concluded that individuals who are carrying the G allele of the IL-1β rs1143634 SNP slowly progress from using mechanical ventilation systems or death outcomes." (PMID 39452786, 2024). "Through the application of Mendelian randomization methodology, two immune genes, CD1C and IL1B, have been identified as exhibiting the closest association with COVID-19." (PMID 39622956, 2024). "In severe cases of COVID-19, patients often suffer from an overreaction of the immune system, which is caused by the release of other cytokines such as IL-1β and TNF-α in a condition called cytokine storm." (PMID 38251210, 2024). "COVID-19 viral infection compared to infection caused by other viruses is characterized by increased pro-inflammatory cytokine levels such as IL-6, IL-1β, and TNF-α." (PMID 39063142, 2024). "We aimed to investigate the association of IL-6R rs12083537, IL-1β rs16944, and IL-1β rs1143634 SNPs with the severity of COVID-19." (PMID 39452786, 2024). "Research has shown that peripheral blood mononuclear cells (PBMCs) from individuals with COVID-19 display inflammasome signatures linked to IL-1β, as evidenced by flow cytometry and single-cell transcriptomic analyses." (PMID 39518964, 2024). "Thereby, we aimed to investigate the association of IL-1β (rs16944 and rs1143634) and IL-6R (rs12083537) SNPs with COVID-19 severity among the Egyptian population." (PMID 39452786, 2024). "Among the inflammatory mediators induced by COVID-19, two of the major pro-inflammatory cytokines, IL-1β and TNFα are each capable of causing mtDNA damage and dysfunction, decreasing ATP levels in cells." (PMID 40603504, 2024). "The IL-1β (rs16944) CC genotype and IL-6R (rs12083537) GG genotype were substantially related to COVID-19 severity, which was also associated with comorbidities and some laboratory parameters (p < 0.001)." (PMID 39452786, 2024). "A considerably higher amount of IL-1β in the bronchoalveolar lavage (BAL) fluid of COVID-19 patients was also linked with illness severity." (PMID 39452786, 2024). "It has been shown that severe COVID-19 is associated with a significant derangement in proinflammatory cytokines, namely, IL-1β, IL-2, IL-6, IL-8, or TNF-α, often referred to as the “cytokine storm”." (PMID 37762549, 2023). "The expression of caspase-4 in the lungs of COVID-19 patients showed an association with the levels of inflammasome activation markers such as caspase-1, IL-1β, IL-6 and IL-18." (PMID 37251383, 2023). "In this study, the expression of NLRP1, NLRP3, and ASC and their association with serum level of IL-1β were explored in COVID-19 patients." (PMID 37723427, 2023). "Acute COVID-19 was associated with marked elevations in nearly all pro-inflammatory markers, whilst eleven markers (namely IL-1β, IL-2, IL-6, IL-10, IL-18, IL-23, IL-33, TNF-α, IP-10, G-CSF and YKL-40) were associated with disease severity." (PMID 37063871, 2023).
COVID-19 (continued). "Compared to other viral diseases such as influenza, COVID-19 generally has higher TNFα/IL-1β-associated inflammation and lower interferon responses." (PMID 37090709, 2023). "Most severe cases of COVID-19 with respiratory distress syndrome were associated with high systemic levels of IL-1β, TNF-α, and IL-6." (PMID 37112918, 2023). "As we observed that the expression levels of NLRP3/IL-1β were downregulated in the innate immune cells from COVID-19 patients, we wanted to further explore the protein encoded by the SARS-CoV-2 genome involved in the downregulated NLRP3 inflammasome pathway." (PMID 38004809, 2023). "This design employs external deliberate specific intervention on a proposed cause of disease (excessive IL-1β for the case of anakinra trials) to assess effect on outcome or clinical course of COVID-19." (PMID 37928695, 2023). "Excessive production of IL-1β has been linked to several inflammatory and autoimmune diseases, including severe COVID-19 and dry eye disease." (PMID 37446547, 2023). "Due to the association of uncontrolled inflammation with severe COVID-19 and unfavorable outcomes, we investigated IL-6, IL-1β, and TNF as inflammatory markers in the respiratory track." (PMID 37752151, 2023). "On the other hand, FFAR2 and FFAR4 have been shown to downregulate Th2 inflammatory pathways implicated in cytokine storm in severe COVID-19 cases, including inflammatory cytokines IL-1β and IL-6." (PMID 37515117, 2023). "Other genes commonly associated with COVID-19 immune responses (e.g., Stat1, Myd88, Il1b Nlrp3, Cdkn1a, and Casp1) were also upregulated in responder brains." (PMID 36739463, 2023). "For example, the cytokine IL-1β showed no differential representation between the deceased and recovered COVID-19 patients (p = 0.9701), while the model-corrected IL-1β level was significantly associated with COVID-19 mortality (p = 1.161e-3)." (PMID 37735372, 2023). "Studies indicate that the potential activation of the NLRP3 inflammasome by SARS-CoV-2 directly leads to elevated levels of pro-inflammatory cytokines IL-1β and IL-18 in severe COVID-19 patients, which are associated with adverse outcomes." (PMID 38193087, 2023). "Down-regulation of SIRT 1 in COVID-19 is associated and highly correlated with elevated levels of IL-1β, IL-6, IL-8, and TNF-α." (PMID 37486805, 2023). "Critical and fatal COVID-19 outcomes in adults have been associated with elevated levels of mostly IL-6, IL-1β, and TNF-α, along with a reduced and delayed production of type I IFNs." (PMID 37047752, 2023). "Our findings that increased GCF IL-1β levels were associated with increased COVID-19 also support this assumption." (PMID 36718446, 2023). "The findings suggests that periodontitis and the higher GCF IL-1β levels is causally related to increase susceptibility of COVID-19." (PMID 36718446, 2023). "The pro-inflammatory cytokine IL1B, which encodes IL-1, is one of the key mediators in inducing innate immune response-mediated inflammation in COVID-19 patients’ lungs." (PMID 37053191, 2023). "COVID-19 can cause acute respiratory syndrome with consequent release of proinflammatory cytokines, including interleukin-1β (IL-1β) and IL-6, from the respiratory tract." (PMID 36752623, 2023). "This suggests IL-1β blood levels are minimally elevated, if at all, in COVID-19 patients independently of assay deficiencies." (PMID 37928695, 2023). "Several studies have reported that the use of anakinra, a dual blocker of IL-1α and IL-1β, in COVID-19 patients reduced the mortality risk, especially in the presence of signs of hyperinflammation." (PMID 37986089, 2023). "Elevated serum levels of IL-1β have been observed in severe cases of COVID-19, and these increased levels are associated with the worsening of the disease." (PMID 38090572, 2023).
COVID-19 (continued). "In previous studies, the JAKs/STAT3 for signal transduction can activate pro-inflammatory gene expressions and facilitate the NLRP3 inflammasome to secrete IL-1β and IL-18 during the pathogenesis of COVID-19-associated neurodegenerative diseases." (PMID 36698809, 2022). "In severe COVID-19 cases, the hallmark of this infection is the release of inflammatory products, which includes IL-1B along with the cytokine storm." (PMID 36016187, 2022). "The increased mortality of many severely ill COVID-19 patients has been linked to the excess production of proinflammatory cytokines (e.g., IL-6, IL-1β, TNF-α, and interferon) upon SARS-CoV-2 infection, causing multiple organ failure." (PMID 36173315, 2022). "For example, the recent SAVE-MORE trial showed that anakinra, which blocks both IL-1α and IL-1β, reduced the risk of clinical progression in patients with COVID-19, when co-administered with dexamethasone." (PMID 36505497, 2022). "Specifically, we identify lower levels of LPS-stimulated IL-1β, and R848-stimulated IL-12 and IL-17A, at hospital admission to be significantly associated with increasing COVID-19 disease severity during hospitalization." (PMID 36101705, 2022). "Using single-cell transcriptomic and flow cytometric analyses, some studies have identified that peripheral blood mononuclear cells (PBMCs) from patients with COVID-19 contained IL-1β-associated inflammasome signatures." (PMID 35464491, 2022). "These large-scale data revealed that the serum levels of IL-6, IL-10, IL-2R, TNF-α, IL-1β, IL-4, IL-8, and IL-17 are potential risk factors for severity and high mortality in COVID-19." (PMID 35237162, 2022). "A pathologic hallmark of severe COVID-19 cases is the onset of inflammatory “cytokine storm”, marked by elevated IL1B, TNFA, CCL2, IL6, MIP1A, and IL10 in the plasma." (PMID 35740365, 2022). "Higher IL-17 levels in nasopharyngeal swabs and lung autopsies of COVID-19 patients were associated with higher levels of proinflammatory cytokines, including IL-1β, TNFα, IL-6, IL-8, and IL-23." (PMID 36136963, 2022). "Immune dysregulation, a hallmark of COVID-19 course and severity, is mainly orchestrated by cytokines and chemokines (e.g., IL-6, IL-1β, IL-8, IL-18, TNF-a) that are identified as tumorigenesis drivers." (PMID 36298472, 2022). "The relationship between elevated PCT and COVID-19 severity can be explained by the associated systemic inflammation and the release of the proinflammatory cytokines such as IL-6, IL-1β, and TNF-α, with subsequent induction of PCT synthesis." (PMID 36295550, 2022). "Within the COVID-19 group, IL-1β, IL-8, IL-13, and TNF were negatively associated whereas IL-12, GM-CSF and bFGF were positively associated with days since symptom onset/positive test." (PMID 35222429, 2022). "For example, increased levels of IL-1β are linked to lymphopenia in COVID-19 patients, presumably due to ongoing inflammation-induced pyroptosis." (PMID 36742994, 2022). "In conclusion, we found that serum levels of IL-6, IL-8, and IL-10 were associated with the disease severity of COVID-19 patients, and serum levels of IL-1β, IL-6, and IL-8 were associated with the prognosis of COVID-19 patients." (PMID 35540724, 2022). "Post-acute sequelae of COVID-19, also called Long-COVID, is as HF potentially caused by incomplete resolution of inflammation and characterized by a long lasting elevation of IL-1β, IL-6 and TNF-α." (PMID 35548445, 2022). "Next, we have assessed the association between IL-17, TNFα and IL-1β levels in saliva of severe COVID-19 cases with the survival outcomes of these patients." (PMID 36136963, 2022). "An elevated level of IL-1β and an association with viral load and severity are also reported from COVID-19 patient blood." (PMID 35587188, 2022). "COVID-19 is associated with cytokine storm with exaggerated inflammatory response characterized by release of large amounts of cytokines like IL-1b, IFN-α, IFN-γ, TGF-α, IL-6, IL-12, IL-18, and IL-33." (PMID 35382491, 2022).
COVID-19 (continued). "IL-1β can potentiate IL-6 responses that are heavily implicated in excessive inflammation associated with COVID-19 pathogenesis." (PMID 36817759, 2022). "Analyses of cytokines have shown that serum levels of IL-1β, IL-6, IL-10, IL-23, IL-33 and Gal-1 are in significant positive association with increased COVID-19 severity." (PMID 35075140, 2022). "Among cytokines, interleukin 6 (IL-6), TNF and IL-1β have been identified as key targets associated with PF secondary to COVID-19." (PMID 35308222, 2022). "The activation of IL-1β and IL-6 in COVID-19 has been associated with “cytokine storms”, which can have severe biological and clinical consequences." (PMID 35162148, 2022). "It is important to underline that prolonged activation of NLRP3 leads to an increase in the levels of IL-1β and IL-18 which are associated with more severe forms of COVID-19." (PMID 35566589, 2022). "The plasma IL-1β levels in COVID-19 active cases were significantly associated with circulating neutrophils concentration (r = 0.42, p<0.05) whiles IL-1β levels in COVID-19 unexposed cases was positively associated with Lymphocytes (r = 0.57, p<0.05)." (PMID 36094915, 2022). "Among TNFα or IL-1β saliva levels, higher IL-17 level in saliva of COVID-19 patients was associated with disease severity and worse clinical outcomes, defined as need for mechanical ventilation and/or death within 29 days of admission." (PMID 36136963, 2022). "Serum cytokine levels that are elevated in patients with COVID-19-associated cytokine storm include IL-1β, IL-6, TNF, IFN-γ and MIP-1." (PMID 33397398, 2021). "IL-6 >142.5 pg/mL, IL-10 >10.8 pg/mL, IL1β > 4.68 pg/mL, sIL-2rα >804.5 pg/mL, IL-1Ra >88.4 pg/mL, and IL-18 > 144 pg/mL values were associated with the development of critical COVID-19 in the age-adjusted univariate analysis." (PMID 34422145, 2021). "Together, these data suggest a limited contribution of the IL-1β and IL-18 pathways and inflammasome activation to COVID-19–associated clinical outcome." (PMID 33232303, 2021). "Regarding the significant association for IL-1β with antibody response, the use of IL-1β agonists to treat COVID-19 patients needs to be carefully evaluated." (PMID 33763078, 2021). "In fact, most COVID-19 patients with severe illness have increased levels of IL-1β, which is associated with ARDS; therefore, inhibition of IL-1β can mitigate development of the cytokine storm that causes death in COVID-19 patients." (PMID 34276659, 2021). "Dysregulated IL-1β and IL-6 responses have been implicated in the pathogenesis of severe Coronavirus Disease 2019 (COVID-19)." (PMID 33319166, 2021). "In COVID‐19, the increased amounts of cytokines (e.g. IL‐1β, IFN‐γ, IP‐10, IL‐10 and IL‐4) is associated with COVID-19 severity." (PMID 34118952, 2021). "These included MCP1, IL-6, IL-1β and TNFα, which are typical components of the cytokine storm associated with respiratory failure and high mortality in COVID-19 patients." (PMID 34807265, 2021). "HLH has been linked to NET induction and production of cytokines such as IL-1β, IL-6, IL-8 and IL-17, elevated in both KD and COVID-19." (PMID 33684134, 2021). "Our results also illustrated that the serum levels of IL-1β, TNFα, IL-6, IL-12, IL-23, and IL-33 are risk factors associated with COVID-19 severity." (PMID 34917631, 2021). "Elevated levels of other proinflammatory cytokines like IL-1β and IL-6 in both infected lungs and plasma have been linked to COVID-19 severity." (PMID 34403366, 2021). "A common clinical complication associated with COVID-19 is acute respiratory distress syndrome (ARDS) attributed to a cytokine storm of IL-1β, IL-6, IFN-γ, and TNF, among others." (PMID 34445140, 2021). "TNFα and IFNγ are known to particularly drive COVID-19 disease severity and in addition, IL-6, IL-1β and IL-12 have been consistently implicated in severe disease." (PMID 33813138, 2021).
COVID-19 (continued). "Recent clinical reports have shown that inflammation was induced in COVID-19 cases, and this induction was associated with an increased level of cytokines, including interleukins (IL-1β, IL-6, IL-10) and tumor necrosis factor-α (TNF-α)." (PMID 34901061, 2021). "The magnitude of senescence led to a high surge of IL6, IL1b, IFNγ, C-reactive protein, and TNFα is reported in several epidemiological studies to lower airway and lung injury and risk for in COVID-19 elderly patients." (PMID 33815889, 2021). "All of these cytokines (TNFα, IL-1β, IL-6) were found in high levels in COVID-19 patients and associated with severe disease outcomes." (PMID 34163462, 2021). "The coronavirus disease 2019 (COVID-19) is associated with cytokine dysregulation, increased IL-1β, tumor necrosis factor (TNF) and IL-6 release with hyperinflammation and risk of CSS." (PMID 33562758, 2021). "In severe COVID-19, the expression of IL-1α, IL-1β, and IL-1 receptor and their associated downstream signaling molecules were induced before respiratory function worsened." (PMID 34176095, 2021). "It was reported that IL-1β increased in COVID-19 patients and was associated with the disease severity." (PMID 32985562, 2020). "CDCs target multiple cytokine pathways (e.g., TNFα, IFN-γ, IL-1β, IL-6) that are associated with disease progression and poor outcomes in COVID-19." (PMID 32399655, 2020). "COVID-19 infects the upper and lower respiratory tract, causing the release of pro-inflammatory cytokines such as interleukin 1β (IL-1β), tumor necrosis factor (TNF), and IL-6." (PMID 32802622, 2020). "Symptoms of severe COVID-19 have been associated with a cytokine storm with high levels of IL-17, IL-10, IL-1β, IL-2, IL-7, IL-8, IL-9, among many other pro-inflammatory cytokines." (PMID 33071815, 2020). "High levels of IL-6 and IL-1β drive the cytokine storm in severe COVID-19 patients, causing organ injuries and MODS." (PMID 33986658, 2020). "Reports of patients with severe COVID-19 indicate that elevated levels of IL-1β and IL-6 are associated with elevated immune exhaustion and reduced T cell functional diversity." (PMID 32655582, 2020). "In COVID-19, patient CT lung scan with multiple bilateral lobular pneumonia is associated with IL-1β, IL-7, IL-8, IL-9 level increase in initial plasma concentration." (PMID 32961074, 2020). "TLR-2, TLR-3, and TLR-4 activation by COVID-19 causes the release of inflammatory cytokines such as IL-1β." (PMID 33082858, 2020). "These immune reactions, particularly cytokine storms, are also observed in severe COVID-19 cases and may help contextualize a potential role for IL1B variants in modulating disease severity." (PMID 40506975, 2025). "Angiotensin II subsequently activates the nuclear factor kappa B (NF-κB) pathway, a key regulator of inflammation, which is also stimulated by other cytokines implicated in COVID-19, such as IL-1β, IL-6, TNF-α, IL-10, MCP-1, AT1, and platelet-derived growth factor beta (PDGF-B)." (PMID 40869200, 2025). "SARS-CoV-2 infection induces the release of proinflammatory cytokines, including IL-1β and IL-6, which may contribute to the development of interstitial pneumonia, a hallmark of severe COVID-19." (PMID 40406515, 2025). "Given the importance of IL-1β in promoting severe SARS-CoV-2-induced disease in our model and mounting evidence for a critical role of this cytokine in driving severe human COVID-19, we further investigated the contribution of IL-1β in age-associated severe COVID-19." (PMID 40016339, 2025). "Notably, activated macrophages produce IL1-β as a proprotein, which has been implicated in severe COVID-19-related cytokine storms." (PMID 40370730, 2025). "This study significantly advances our understanding of COVID-19 severity by evaluating a comprehensive panel of cytokines and clinical markers, confirming the robust association between elevated levels of IL-1β, IL-6, IL-8, IL-10, IL-17A, IL-23, TNF-α, and IFN-α with critical disease outcomes." (PMID 39861879, 2025).